Y_RNA (Y RNA )
Gene: Miscellaneous RNA gene on chromosome 5 (172,779,982 to 172,780,094, reverse strand). Ensembl gene ENSG00000206741.
Homologues: Orthologues: chimpanzee Y_RNA (100% identical), macaque Y_RNA (96% identical). Paralogues in human: Y_RNA (88% identical), RNY1 (86% identical), Y_RNA (86% identical), Y_RNA (85% identical), Y_RNA (84% identical), RNY1P11 (83% identical), Y_RNA (83% identical), Y_RNA (82% identical), Y_RNA (81% identical), RNY1P10 (81% identical), RNY1P8 (81% identical), Y_RNA (80% identical), and 98 more.